CDK9 (cyclin dependent kinase 9)
Diseases named in the same sentence as CDK9 in open-access papers (continued):
Sharing a sentence is not in itself a finding about the gene and the disease.
cancer (continued). "We observed that CDK9 and BRD4 inhibition reduced butyrate-triggered NCOA4 expression, decreased Erastin, RSL3 and butyrate-induced cell death; in contrast, BRD4 inhibition by JQ1 triggered ferritinophagy and ferroptosis in cancer cells." (PMID 33298848, 2020). "However, CDK9-specific inhibitors, such as BAY 1143572 (NCT01938638), are beginning to enter clinical trials in patients with advanced cancer and will evaluate MYC expression as a biomarker." (PMID 33322239, 2020). "Thus the predominant pharmacological effect of fadraciclib on cancer cells is likely to be mediated by inhibition of CDK2 and CDK9." (PMID 32645016, 2020). "CCNB1IP1, CCNC, CCND2, CDK5R2, CDK9, and GAK were upregulated in all three cancer regions." (PMID 33302383, 2020). "Cdc7 and Cdk9 are seen as promising targets in cancer, and multiple compounds targeting these kinases, including PHA-767491, have been investigated for potential anti-cancer effects in preclinical studies and clinical trials." (PMID 31402912, 2019). "As our understanding of biological pathways regulated by HSF1 in supporting cancers deepens, such as the role of the PIKK family, CDK9, and Pirin in the inhibition of the HSF1 stress pathway, identification of new chemotypes as potential candidate for cancer therapy will be easier." (PMID 30356024, 2018). "Notably, the most sensitive cancer cells lines included hematologic tumor cells, especially AML, thereby providing functional evidence for the dependency of AML on the CDK9 pathway." (PMID 29471852, 2018). "Dinaciclib (SCH 727965, Merck) is a pyrazolo [1,5-α]pyrimidine that potently inhibits CDK1, CDK2, CDK5, and CDK9 with IC50 values ranging from 1 to 4 nM in a broad spectrum of human cancer cell lines including MCL, NHL, leukemia, colon, pancreatic, breast, prostate, SCLC, liver, and bladder." (PMID 25914884, 2015). "Our own studies have also demonstrated that CDK9 inhibitors can achieve anti-cancer activity with minimal toxicity to non-transformed cells." (PMID 25277198, 2014). "Given the clear clinical importance of MCL1 in CLL, we rationalized that targeted inhibition of cdk9 might prove to be a useful therapeutic strategy in CLL and other cancers in which MCL1 is over expressed." (PMID 24495868, 2014). "Furthermore, cancer cells harbouring CCNE1 gene amplification displayed a higher sensitivity to the CDK1, CDK2 and CDK9 small molecule inhibitor AZD5438 than cancer cells lacking CCNE1 gene amplification (t-test, P = 0.019)." (PMID 22433433, 2012). "Similarly to CDK9, CDK7 also has a bidirectional relationship with BRD4 whereby both are substrates for each other, creating a regulatory loop that is important for gene transcription in cancer." (PMID 40163908, 2025). "Clinical data from ongoing trials will further clarify whether CDK9 inhibitors can achieve selective therapeutic efficacy against MYC-dependent cancers without prohibitive toxicity." (PMID 40365020, 2025). "Like other targeted therapies in cancer, CDK9 inhibition alone may not be sufficiently efficacious as single-agent therapy." (PMID 39117800, 2024). "Indeed, engineered CDK2, but not CDK9 over-expression, reversed the presence of cancer cells having multipolar mitoses or chromosome ring formations after treatment with CYC065 or transfection of siRNAs that targeted CDK2." (PMID 38031910, 2023). "Notably, engineered gain of CDK2, but not CDK9 expression, reversed emergence of cancer cells with chromosome rings or multipolarity, despite CYC065-treatment." (PMID 38031910, 2023). "Therefore, inhibiting CDK9, BRD4 and SEC in combination could prove to be a highly effective trident of inhibitors against cancers, especially against the cMYC driven ones." (PMID 34062779, 2021). "Although the expression of CDK9 in ESCC remains unclear, studies have demonstrated that CDK9 is overexpressed in many human malignant tumors and has been considered as an excellent target for drug development in cancer." (PMID 34741018, 2021).
cancer (continued). "In cancer cells, YAP/TAZ tends to predominantly promote the transcription of their target genes by recruiting Mediator complex to the enhancers, and this further recruits CDK9, thus activating transcription elongation of YAP/TAZ target genes implicated in tumorigenesis." (PMID 33467099, 2021). "The pharmacological CDK9 down-regulation may lead to increased C-MYC expression in human cancer cells, although the results described here do not accommodate such compensatory mode." (PMID 32632086, 2020). "Additionally, combining CDK9 and BET inhibitors synergistically improves anti-proliferative activity in several cancers, with no hematological toxicity or weight loss shown in vivo." (PMID 33322239, 2020). "Intensive research in the cancer field has unraveled the role of BET proteins in NF-κB pathway regulation, demonstrating that BRD4 binding to acetylated lysine-310 of RelA is essential for recruiting BRD4 and CDK9 to the promoters of specific NF-κB target genes." (PMID 30647531, 2018). "The CDK9-inhibiting module from HEXIM1 could indeed be combined with functional domains from transactivator targets other than Tat, allowing this strategy to be applied to other pathologies, including inflammation or cancer." (PMID 30395647, 2018). "These suggest that down-regulation of Mcl-1 protein expression may be necessary, but not sufficient for induction of apoptosis, whereas CDK9-targeted transcriptional inhibition of Mcl-1 should be more effective apoptotic strategy in cancer cells." (PMID 25277198, 2014). "CDK9 is the kinase with the most specific function limited to regulation of transcription; this selectivity confers the ability to inhibit pol II phosphorylation rather than cell cycle CDKs or other kinases and to target noncycling cancer cells." (PMID 19674456, 2009). "However, in cancer, the role of CDK9 in mitochondrial function has not been elucidated." (PMID 31398271, 2019). "With the combined inhibition of CDK9-mediated transcription and Mnk-eIF4E translation, together with its low toxicity in non-transformed cells and favourable pharmacological properties manifested, CDKI-73 may offer an opportunity to treat a wide range of human cancers." (PMID 25277198, 2014). "Additionally, unlike CDK9, the genetic alterations of BRD4 also occur with increasing frequencies in different cancer entities." (PMID 34062779, 2021). "Although CDK9 inhibition suppresses MCL1 expression, it does not affect levels of other anti-apoptotic proteins such as Bcl-xL, exposing a potential vulnerability in CDK9i treatment such that cancers may already have or develop a mode of resistance." (PMID 31294695, 2019).
tumor (160 papers, 2013 to 2026). "We also found that in a cohort of 46 patients with HB, high cyclin-dependent kinase 9 tumor expression was significantly associated with poor prognosis." (PMID 37729391, 2024). "Altogether, these results suggest MCL1 inhibition, either directly or indirectly through CDK9 inhibition, has potent anti-tumor activity in PBRM1-deficient ccRCC." (PMID 38371625, 2024). "Corresponding to this, high CDK9 levels are associated with tumor stage and lower CD8+ T cell infiltration and increased T cell exhaustion." (PMID 36139513, 2022). "We have identified a significant association between CDK9 expression and aggressive clinico-pathological parameters such as high proliferative index (Ki-67), advanced stage and tumor recurrence." (PMID 34011401, 2021). "Since GSCs are critical players in tumor formation and resistance to treatment, this finding supports the utility of targeting CDK9 to reduce treatment resistance caused by GSCs." (PMID 34207158, 2021). "Tumor growth inhibition was associated with CDK9 inhibitor-mediated fibrosis, which was significantly elevated in the combination group compared with the control (p = 0.002), radiation (p = 0.002), and CDK9 inhibitor (p = 0.009) groups." (PMID 31384397, 2019). "CDK9 inhibitor plus radiation-induced tumor regression was associated with necrosis (p = 0.037 compared to radiation alone)." (PMID 31384397, 2019). "Analysis of the tumour tissues collected from the xenografted animals confirmed that the in vivo anti‐tumour efficacy was associated with CDK9 targeting of CDKI‐73." (PMID 31398271, 2019). "CDK9, a serine/threonine protein kinase of the cyclin-dependent kinase family, regulates transcription by phosphorylating RNA polymerase II and has been implicated in oncogenesis and tumor immune evasion." (PMID 40975978, 2025). "We found 2 cyclin-dependent kinase 9 (CDK9) inhibitors, alvocidib and dinaciclib, acting as potent HB growth inhibitors for the high-risk C2 tumor subtype, which were then further validated in HB patient-derived xenograft (PDX) models grown in vitro and in vivo." (PMID 37729391, 2024). "Therefore, CDK9 inhibition causes the reactivation of epigenetically silenced genes in cancers, restoring the expression of tumor suppressor genes and cellular differentiation." (PMID 36154607, 2023). "CDK9 over-expression was noted in 56.2 % (248/441) of EOCs and was associated with adverse clinico-pathological parameters such as distant metastasis (p < 0.0001), stage IV tumors (p < 0.0001), tumor recurrence (p = 0.0105) and high Ki-67 index (p < 0.0001)." (PMID 34011401, 2021). "CDK9 over-expression was noted in 56.2 % (248/441) of EOCs and was significantly associated with adverse clinico-pathological parameters such as distant metastasis (p < 0.0001), stage IV tumors (p < 0.0001), tumor recurrence (p = 0.0105) and high Ki-67 index (p < 0.0001)." (PMID 34011401, 2021). "As tumor cells frequently upregulate Bcl-2, inhibitors of CDK9 and CDK12/13 represent promising anticancer drugs." (PMID 42204137, 2026). "This TMA analysis revealed that the TNBC tumours were broadly CDK9-positive, with around 75% of tumours showing 80–100% positivity with moderate to strong staining intensity (i.e. histological score 4–9)." (PMID 41505030, 2026). "The role of CDK9 in tumor growth was assessed through mice survival time, in vivo imaging, and immunohistochemistry (IHC)." (PMID 39800696, 2025). "In an OC tissue microarray made with paired primary, metastatic, and recurrent tumor tissues from 26 OC patients, CDK9 expression was identified by immunohistochemistry." (PMID 40361480, 2025).
tumor (continued). "Individual constituents of super enhancers, such as BRD4, CDK7, or CDK9, have demonstrated significant potential in multiple preclinical tumor models." (PMID 39838405, 2025). "Collectively, these analyses demonstrate that CREPT is expressed in most CDK9-positive tumor cells, implying a potential functional interaction or a cooperative role between CREPT and CDK9 in the LUAD tumors." (PMID 40860160, 2025). "The results showed that both CREPT depletion (shCREPT) and CDK9 inhibition (CDK9i) significantly attenuated tumor volume compared to controls." (PMID 40860160, 2025). "It showed reduced tumor bioluminescence signals in the CDK9 knockdown group on day 6, day 9, and day 12 after transplantation." (PMID 39800696, 2025). "In particular, studies showed that combining CDK9 inhibition with ICB increases both T cell and antigen-presenting cell (APC) activation and function compared to ICB alone, demonstrating a function of CDK9 in modulating tumor microenvironment." (PMID 40860160, 2025). "The high co-localization and the interaction of CREPT-CDK9 in tumor cells prompted us to investigate CDK9 expression in LUAD." (PMID 40860160, 2025). "Reciprocally, MYC requires CDK9 to function as a transcription factor that amplifies transcription to drive tumour growth." (PMID 38001268, 2024). "Our drug screening with our newly established CDC preclinical models identified a CDK9 inhibitor LDC000067 that specifically inhibited CDC tumor growth and prolonged survival." (PMID 39122888, 2024). "The same finding is confirmed when considering overall survival; patients stratified according to low and high CDK9 tumor staining have a 3-year overall survival probability of 97% and 66.7%, respectively (Log-rank=0 0.0039)." (PMID 37729391, 2024). "In summary, our work sets the basis for the use of dinaciclib in chemotherapy-resistant SCLC and a rationale to introduce specific CDK9 inhibitors with comparable anti-tumour efficacy and safety profile." (PMID 38769311, 2024). "It exhibits superior inhibition of unanchored tumor sphere growth compared to existing chemotherapy agents carboplatin and 5-fluorouracil or CDK9 inhibitor FIT-039." (PMID 38751791, 2024). "CDK9 inhibition can also decrease phosphorylation of the androgen receptor (AR), decreasing AR-dependent transcription and reducing tumor burden in vivo." (PMID 38172923, 2024). "In vivo, CDK9 inhibition effectively reduced tumour growth and improved survival in both autochthonous and syngeneic SCLC models." (PMID 38769311, 2024). "This study revealed promising anti-tumor activity by CDK9-targeting compounds as a potential therapeutic strategy for KRAS-mutant CRC." (PMID 37569406, 2023). "Tumor cells that become reliant on (or “addicted” to) these products for survival have a heightened sensitivity to CDK9 inhibition." (PMID 38117531, 2023). "As a potential tumor target, there are still many problems to be solved before CDK9 inhibitors and degraders can be applied clinically." (PMID 37272701, 2023). "THAL-SNS-032, which has been relatively extensively studied among CDK9 degraders, has been reported to induce severe gastrointestinal disorders in mouse models owing to an on-target off-tumor effect." (PMID 37272701, 2023). "Pharmacologic targeting of CDK9 has shown promising in vitro and in vivo anti-tumor activity in malignancies that exhibit dependence on Mcl-1 and/or MYC." (PMID 36998071, 2023). "Although these reports are encouraging in that selective CDK9 inhibitors and degraders have been demonstrated to restrain tumor growth in hematological malignancies and solid tumors in vitro and in vivo, many problems still remain." (PMID 37272701, 2023). "Due to the variety of solid tumors and tumor heterogeneity, CDK9 studies in solid tumors are far fewer than those in hematological malignancies." (PMID 37272701, 2023).
tumor (continued). "In preclinical trials, the application of CDK9 inhibitors led to tumor cells apoptosis, tumor growth inhibition and tumor mass reduction." (PMID 35092513, 2022). "P276-00 inhibits tumor cell growth in culture 2 to 3 times stronger than Flavopiridol because of its higher selectivity toward CDK9." (PMID 35092513, 2022). "As for caspase-8, the prognostic/predictive value of CDK9, however, still remains controversial among different tumor types." (PMID 36428594, 2022). "Targeting MED1 phosphorylation by a highly specific CDK9 inhibitor decreases tumor growth through inhibition of Pol II recycling." (PMID 35394046, 2022). "In those settings, CDK9 inhibitors were primarily examined as co-therapeutics to alleviate the resistance to other drugs and enhance anti-tumor properties." (PMID 35092513, 2022). "A pharmacodynamic study in tumor bearing mice has also shown that CDDD11-8 works by potently inhibiting CDK9 and FLT3, similar to the in vitro finding." (PMID 35267421, 2022). "Using CDK9 inhibition as a paradigm, we produced models in which Cdk9 can be systemically suppressed in tumor-bearing mice and compared the results of genetic Cdk9 inhibition to those achieved using a recently developed highly specific CDK9 inhibitor." (PMID 35442775, 2022). "CDK9 inhibition has also been shown to enhance the immune response against tumors by inducing immunogenic cell death (ICD) in tumor cells." (PMID 34207158, 2021). "The data presented here clearly show that CDK9 inhibitors suppress the expression of Sox2 and Sox9, and interfere with anchorage independent growth of tumor cells." (PMID 34359807, 2021). "Future studies will confirm the role of CDK9 in tumour metastasis and chemoresistance and explore the synergistic effects of acetyl-bufalin in combination with other chemotherapies." (PMID 33122847, 2021). "CDK9 is increasingly regarded as a major therapeutic target for developing antitumor drugs due to its important value in tumor growth and the occurrence of virus infection in patients." (PMID 35071768, 2021). "Here, we discuss how CDK9 inhibition can impact transcription, metabolism, DNA damage repair, epigenetics, and the immune response to facilitate an anti-tumor response." (PMID 34207158, 2021). "In preclinical studies, CDK9 inhibitors have demonstrated anti-tumor effects in many different types of tumor." (PMID 33748130, 2021). "The results from the tumor organoids imply that the CDK9 inhibitors would be effective in eliminating the heterogeneous tumors in vivo." (PMID 34359807, 2021). "CDK9 was increased in 10 of the 12 tumour tissues (83.33%) compared with that in the adjacent tissues." (PMID 33122847, 2021). "The results from tumor organoids imply that CDK9 inhibitors are effective in eliminating the heterogeneous cell population in the organoids." (PMID 34359807, 2021). "CDK7 and CDK9 are key regulators of transcription initiation and elongation, respectively, supporting the concept of targeting transcriptional dependencies in tumor cells." (PMID 34215733, 2021). "From CTRPv2, we detected multiple inhibitors of CDK9 predicted to preferentially kill dNER tumor cells." (PMID 34066883, 2021). "A previous study presented CDK9 as a potential target for tumor therapy in combination with TRAIL treatment." (PMID 34663829, 2021). "An extensive screening of kinase inhibitors in a large panel of tumor cell lines also identified CDK9 inhibitors as being particularly cytotoxic for NC cells." (PMID 34176480, 2021). "Although it inhibits other CDK isoforms, including CDK4, CDK5 and CDK7, its primary anti-tumour mechanism is now understood to be through transcriptional regulation via CDK9/P-TEFb." (PMID 33632038, 2021). "No specific IC50 values were disclosed but it claimed to be <10 nM against CDK9 in biochemical assay and <1 nM against cell growth in cell-based assay using 44 CDK9-expressing tumour cell lines, including human acute leukaemia MOM13 cells." (PMID 33632038, 2021).